ASS1P3 (argininosuccinate synthetase 1 pseudogene 3)
Synonyms: ASSP3
Gene: Processed pseudogene on chromosome 9 (78,178,263 to 78,179,512, forward strand). Ensembl gene ENSG00000233947.
Diseases named in the same sentence as ASS1P3 in open-access papers:
ASS1P3 is named in the same sentence as 3 diseases in open-access papers, as found by Europe PMC text mining. Sharing a sentence is not in itself a finding about the gene and the disease. The quoted sentences say what the papers report.
tumor (2 papers, 2019 to 2024). "On the other hand, in the OE-AR-ASS1P3 model, it seems that the AR blocked ASS1P3’s sponging ability, allowing miR-34a-5p interaction and the inhibition of ASS1, therefore increasing tumor growth." (PMID 39585048, 2024). "Co-expression of AR with pseudogene ASS1P3 could block its suppression likely by inhibiting interaction between miR-34a-5p and ASS1P3, thus releasing the former to suppress ASS1 to promote the tumor growth." (PMID 31000693, 2019).
ASS1P3 also shares sentences with these, for which no sentence is quoted: renal cell carcinoma (2 papers); renal carcinoma (1).